CDH5 (cadherin 5)
Diseases named in the same sentence as CDH5 in open-access papers (continued):
Sharing a sentence is not in itself a finding about the gene and the disease.
tumor (continued). "We took advantage of the orthotopic, genetic murine GBM model with a native microenvironment, induced by RCAS/N-tva-mediated somatic PDGF gene transfer in Ink4a-Arf−/−;Pten−/− neural stem/progenitor cells, followed by tumor transplantation into the new generated Cdh5-CreERT2;Il6fl/fl mice." (PMID 29422647, 2018). "Although the expression of six endothelial differentiation marker genes (PECAM1, vWF, FLT1, FLT4, KDR, CDH5) was significantly lower in normal and tumor ADSC, there was significantly greater expression of PDGFRB in ADSC when compared to BEC and NORMA1 MEC cells." (PMID 26968831, 2016). "Cdh5 expression is required for tumor angiogenesis and blocking their expression with monoclonal antibodies in mouse tumor models leads to the inhibition of tumor growth." (PMID 23285103, 2012). "Importantly, in the case of Cdh5 and the tumor suppressors Mcc and Reck tumor cells are largely unstained while the underlying stroma and the control lung tissue was positive." (PMID 19812696, 2009). "Regulation of claudin 5 expression by cadherin 5 may therefore reinforces such crosstalk between tight and adherens junctions to promote tumor growth and metastasis." (PMID 19812696, 2009). "In addition, CDH5 was positively or negatively correlated with tumor prognosis." (PMID 37809080, 2023). "To investigate the role of GLS in tumor vasculature, we crossed C57BL/6 mice harboring floxed GLS alleles (GLSfl/fl, referred to as WT) with C57BL/6 mice expressing tamoxifen-inducible Cre recombinase (CreER) under the control of the Cdh5/vascular endothelial-cadherin gene promoter." (PMID 36381236, 2022). "Notably, MED samples showed a similar epithelial cell content as in EBUS samples though with a stronger expression of markers of the tumor microenvironment (TME) (CDH5, PTPRC aka CD45, and ACTA-2) which, on the contrary, were absent in pure epithelial LNmets (EBUS samples)." (PMID 36587234, 2022). "Based on the known annotation of marker genes from the literature, we grouped cells of nine clusters into four cell types: GNP-like tumor cells (expressing Math1 and Grin2b), microglia (expressing Aif1 and Cd68), T cells (expressing Cd3d and Cd3e), and endothelial cells (expressing Cldn5 and Cdh5)." (PMID 34210306, 2021). "Several hub genes, such as CDH5, CLDN5, VWF, and PECAM1, were significantly upregulated, reflecting their established involvement in vascular development and tumor progression." (PMID 41008787, 2025). "We found that genes involved in EMT—CDH1, CDH5, and ZEB1—allowed for the differentiation of healthy cells from tumor samples." (PMID 40332096, 2025). "The genes that most characterize EndMT in different tumor types are PECAM1, VWF, CD34, CDH5, MCAM, and CLDN5/11." (PMID 40650130, 2025). "In the colon-derived cells, during the transition from a healthy to a tumor cell and then to a metastatic cell type, we observed a gradual increase in the EMT-TF genes SNAI2 and ZEB1, and in VIM, CDH5 and MMP2." (PMID 40332096, 2025). "Towards that end, we generated heterozygous Rosa26LSL-iCOUP x Rosa26LSL-tdTomato inducible reporter mice driven by Cdh5-CreERT2, implanted PyMT or KPC tumors orthotopically, and then treated tumor-bearing mice with limiting doses of tamoxifen." (PMID 40796746, 2025). "Although the expression of VE-Cadherin (CD144 or CDH5) has been correlated with an endothelial context, its role in the transformation of tumor cells has received increasing attention in the last decades." (PMID 36797281, 2023). "The results indicated that the expression of tumor cell-derived VEGFA, IGFBP3, EFNA1, EFNB1, IGF2, PDGFA and stroma-derived Angpt2, Cdh5, Esam, Esm1, Icam2, and Tie1 was statistically correlated with that of Pecam1 and elevated in p-EMT TW2.6 tumors." (PMID 34869001, 2021). "At the 3-week end point, the vasculature in tumor xenografts was examined by western blot analysis and immunostaining to detect VEGFA and endothelial cell marker VE-Cadherin (Cdh5)." (PMID 33351793, 2020).
tumor (continued). "Significantly, the expression of ADAMTS1 was upregulated during differentiation of GICs with a similar pattern to endothelial-related CDH5 and ENG genes, supporting the existence of an intrinsic endothelial-like nature within these tumor-promoting cells." (PMID 33396280, 2020). "To investigate the role of YY1 in tumor ECs in vivo, we generated EC-specific YY1 knockout mice by crossbreeding YY1flox/flox with Cdh5-CreERT2 transgenic mice to create YY1iΔEC(Cdh5-CreERT2; YY1flox/flo) mice." (PMID 33235311, 2020). "Suggestively, we found that the endothelial-related genes CDH5 and KDR appeared as significant poor prognosis factors in these neoplasias." (PMID 32230715, 2020). "Based on logFC and Betweenness Centrality index values for network nodes, tumor VM formation-related genes, namely, KDR, FLT1, and CDH5, were revealed to be important upregulated hub genes." (PMID 30674871, 2019). "Concomitantly α2β1 down regulated the expression of two other tumor suppressors, namely PKP1 (plakophilin 1) and CDH5 (chromodomain helicase DNA binding protein 5)." (PMID 30197754, 2018). "The influence of the following clinicopathological parameters on the chance of developing distant metastasis was investigated: tumour size (continuous variable), tumour grade, vascular invasion, lymph node status, ER, PR, HER2 status and CDH5:HPA ratio." (PMID 27010749, 2016). "CDH5 and VEGF are recognised mediators of tumour angiogenesis, a process required for invasion and metastasis of solid tumours, and VEGF inhibitors have been approved for the treatment of advanced cancer." (PMID 27010749, 2016). "Using the inducible endothelial specific Cdh5(PAC)-iCreERT2 line, we show that ERG is required for angiogenesis in the developing retina of newborn mice and for tumor blood vessel growth in adult mice." (PMID 25584796, 2015). "Traditionally, angiogenesis has been assessed using markers including von Willebrand factor (vWF), VE-cadherin (also known as cadherin-5) and PE-CAM (CD31), and has been found to be increased in tumour tissues compared with normal tissues." (PMID 16430777, 2006). "Non-tumor components included endothelial cells (expressing VWF, CDH5, ECSCR, SLCO2A1, and MYCT1), pericytes (marked by RGS5, MCAM, and PDGFRB), normal oligodendrocytes (showing PTGDS, MBP, TF, and MOG expression), and TAMs (identified by CD14, AIF1, FCER1G, FCGR3A, TYROBP, and CSF1R)." (PMID 41394801, 2025). "EGFR and IDH1 were highly expressed in tumor cells, FAP and COL1A1 were confined to fibroblasts, CD68 and ITGAM marked macrophages, PECAM1 and CDH5 identified endothelial cells, OLIG2 and MOG were specific to oligodendrocytes, while CD4 and CD3D defined T-cell subsets." (PMID 41208987, 2025). "High expression of CDH5 can enhance CD8+ T cell activity, thereby suppressing tumor growth." (PMID 40427243, 2025). "CDH5, ID1, H2BC10, and ITLN1 were common DEGs in the tumor and stroma areas." (PMID 40422184, 2025). "A total of 3842 endothelial cells from seven tumor samples and one paracancerous tissue were obtained from the GEO database, based on the marker genes VWF, CDH5, RAMP2 and CLDN5,26, 27 of which 3724 and 118 cells were derived from cancer tissues and paracancerous tissue, respectively." (PMID 37726969, 2023). "Notably, when we examined CDH5 expression in the MDA-MB-231-LM2 and AsPC-1 tumours harvested from mice, we observed a significant increase in expression." (PMID 34552183, 2021). "We observed a decrease of tumor myeloid cell Shb mRNA in the tamoxifen treated Cdh5-CreERT2/Shbflox/flox mice, which was not present when the mice had undergone a preceding bone marrow transplantation using wild type bone marrow." (PMID 31101877, 2019). "In both Cdh5 and Sox18-driven lineage tracing models, a discrete population of YFP+ lymphatic vessels could be observed by D15 within the center of the tumor." (PMID 30604758, 2019).
tumor (continued). "Second, tumor subsets enriched for microenvironment features, including hypoxia markers (e.g., Slc2a1, Pdk1, Car9), extracellular matrix (ECM) genes (e.g., Matn2, Fn1, Dcn, Col6a1), vasculature (e.g., Cdh5, Pecam1, Vwf), and interferon response genes (e.g., Rsad2, Ifit3, Gbp3, Cxcl10, Cd274)." (PMID 40171265, 2025). "After that, we analyzed the protein expression levels of CDH5, MMP9 and MAPK1 in normal kidney tissues and ccRCC by CPTAC database, MMP13 for included in CPTAC database, and the protein expression levels of CDH5, MMP9 and MAPK1 were significantly higher than that in normal tissues in tumor tissues." (PMID 38580922, 2024). "PKCα increases lead to the phosphorylation of vascular endothelial-cadherin (VE-cadherin, also known as cadherin-5 and CD144) that resulting in the disassembly of VE-cadherin and protein displacement, leading to enlarged gaps between endothelial cells and an increase in tumor vascular permeability." (PMID 35992357, 2022). "We next performed Matrigel plug in vivo angiogenesis assay using FACS sorted reporter-negative tumor cells (mCherry-) and or reporter-positive iGEC or nGEC (CDH5-mCherry +) to determine if they integrate into host vasculature or induce angiogenesis when embedded subcutaneously." (PMID 36261421, 2022). "A total of 225 high-quality cells from control and 356 from tumor-draining LNs were included in the downstream analysis and their LEC identity could be confirmed by the expressions of endothelial cell markers Cd31 (Pecam1) and VE-cadherin (Cdh5) as well as lymphatic markers Prox1 and Vegfr3 (Flt4)." (PMID 35892863, 2022). "Indeed, our results support a main involvement of CDH5-related pathways, but not strictly from endothelial origins as originally hypothesized, according to their relevant expression in plastic tumor cell populations." (PMID 32230715, 2020). "Given the number of mutations and the nature of the mutations found, including at least one tumor suppressor gene, TP73, and several genes that may be associated with other types of malignancy (ATM, CDH5, MAGED1), WDPM clearly appears to be a functionally benign neoplasm and not a reactive process." (PMID 32545767, 2020). "Immunofluorescence staining on tumor tissues found that the expression level of CD31, a blood vessel marker, was significantly decreased in tumors from WT mice after the treatment of STING agonist, but not in tumors from Stingfl/fl/Cdh5-Cre mice." (PMID 39817453, 2025).
cancer (175 papers, 2008 to 2026). A tumor composed of atypical neoplastic, often pleomorphic cells that invade other tissues. "CDH5 is linked to vasculogenic mimicry (the capacity of cancer cells to form new blood vessel-like channels) in uveal melanoma, glioblastoma stem-like cells, and other cancers." (PMID 41039222, 2025). "The co-expression analyses results showed that almost all the immune response genes were positively associated with CDH5 in pan-cancers except THCA." (PMID 37809080, 2023). "Multivariate analysis showed that patients with ER-positive cancer with vascular invasion were driving the association between the CDH5:HPA ratio and the formation of distant metastases." (PMID 27010749, 2016). "From these clusters, five major cell types were identified via classical cell markers, including T cells (CD3E, CD8A, CD3D), B cells (CD19, MS4A1, CD79A), myeloid cells (CD14, CD68, LYZ), endothelial cells (PECAM1, VWF, CDH5) and cancer-associated fibroblasts (CAFs) (ACTA2, FAP, PDGFRB)." (PMID 39941131, 2025). "Aberrant expression of CDH5 has been observed in cancer and was associated with VM." (PMID 39172098, 2024). "In addition, we also performed the co-expression analyses to further study the associations between CDH5 expression and immune response genes in pan-cancer." (PMID 37809080, 2023). "Elevated expression of transcriptional regulator inhibitor of DNA binding 1 (ID1) promoted cancer cell‐mediated vasculogenic mimicry (VM) through regulation of pro‐angiogenic and pro‐cancerous genes (e.g. VE‐cadherin (CDH5), TIE2, MMP9, DKK1)." (PMID 40116596, 2025). "More specifically, reducing ID1 lowered cancer cell expression of endothelial cell genes (e.g. CDH5, TIE2) and production of pro‐angiogenic proteins (e.g. VEGF, CD31, MMP9 and IL‐8)." (PMID 40116596, 2025). "Among 36 genes, MMP1, HSP90B1, PTK2, MMP3, NOTCH1 and CDH5 had higher methylation status at pan-cancer level." (PMID 38694917, 2024). "PECAM1 expression was closely associated with other well-established TAE markers such as CDH5 (R = 0.94) and TIE1 (R = 0.93) in cancer str of the CRC tumors." (PMID 38557819, 2024). "CIBERSORT was used to analyze the correlations between CDH5 and different immune cell infiltration in pan-cancer." (PMID 37809080, 2023). "We further studied the association between CDH5 and TMB or MSI in pan-cancer, which all showed a significant relationship with the sensitivity of ICIs." (PMID 37809080, 2023). "In the present research, we investigated the correlation between CDH5 and the clinical features of cancer patients." (PMID 37809080, 2023). "CDH5 is abnormally expressed in a variety of human cancers and plays an important role in angiogenesis." (PMID 34358255, 2021). "Collectively, these findings manifest that compartment switching induced by Arid1a depletion modulates the transcription of some cancer-related genes, such as Pmp22, Atg10, Gsc, Rnf125, and Cdh5, which have been known to be involved in tumorigenesis." (PMID 34689165, 2021). "For stroma, the marker genes used were VWF, ENG, and CDH5 (for endothelial cells), DCN, ACTA2, and FAP (for cancer-associated fibroblasts), and PTPRC, CD4, and CD163 (for leukocytes)." (PMID 33810510, 2021). "The silencing and promoter hypermethylation of tumor suppressor gene MLH1 and CDH5 have been reported in various cancers." (PMID 26683359, 2016). "Multivariate analysis showed that the association between CDH5:HPA ratio and the formation of distant metastases was driven by patients with oestrogen receptor (ER+) positive cancer with vascular invasion (VI+)." (PMID 27010749, 2016). "Particularly, many cancer-related genes including CDH5, BVES, CX3CL1, FGFR1, IGF1 and CD40 were identified in SIN_D." (PMID 25774687, 2015). "Furthermore, CDH5 expression facilitates cancer cell transmigration through endothelial barriers and promotes vasculogenic mimicry, pivotal events for cancer cell progression and metastatic colonization of distant organs." (PMID 41039222, 2025).
cancer (continued). "Additionally, we examined the correlation between ESR1 and CDH5 across 34 different cancer types, which showed a significant positive correlation in most cancer types, including BLCA." (PMID 40665298, 2025). "Of note, whereas the α2β1 integrin has a widespread expression, the αIIbβ3 integrin expression is limited to a select number of cell types, which also express CDH6 (as oligodendrocyte progenitors) or CDH5 (as late spermatids and lymphatic endothelial cells), or to several cancer types." (PMID 41039222, 2025). "In particular, we found that in the lung a trend toward an increase in VIM, as well as of the CDH5, MCAM, and MMP2 mRNAs associated with the metastasis-derived cancer cell lines, whereas the MMP9 gene seemed to be mainly related to the mesenchymal phenotype of these cells." (PMID 40332096, 2025). "We then detected the expression of CDH5 across different World Health Organization cancer stages, and found that CDH5 was high-expressed in stage I of BLCA, BRCA, KIRC, and SKCM when compared with higher stages but it was low-expressed in stage I of KIRP and THCA." (PMID 37809080, 2023). "Our findings suggested that CDH5 played an important role in cancer immunity." (PMID 37809080, 2023). "Similarly, the application of the R-package Survminer revealed the prognostic significance of CK19 at primary diagnosis as well as of other cancer-related (CDH5 and TERT) and EMT markers (FAM83A, PTHLH, and ERBB3) at disease progression." (PMID 34834576, 2021). "Therefore, CDH5 has two functions in angiogenesis and cancer progression." (PMID 36899372, 2023). "As most human cancer is epithelial in origin, our focus will be E-cadherin and its related catenins, with occasional discussion on roles of other classical cadherins, such as neural cadherin (N-cadherin, encoded by CDH2) and vascular cadherin (VE-cadherin, encoded by CDH5)." (PMID 37255594, 2023). "We then checked the expression of the canonical cell-type markers: cancer/epithelial cell marker genes (Cdh1, Krt18, and Krt5); mesenchymal cell marker genes (Col1a1, Col1a2, and Col3a1); immune cell marker genes (Ptprc, Cd68, and Csf1r); and endothelial cell marker genes (Pecam1, Emcn, and Cdh5)." (PMID 34497807, 2021). "Thus, there are two distinct functions of CDH5 both in angiogenesis and progression of cancer." (PMID 28377727, 2017). "On chromosome 11, 30 SNPs were concentrated in the intergenic region between CDH5 and CDH11, both members of the cadherin family, which are involved in cancer and vascular disease." (PMID 40427243, 2025). "We took advantage of a genetic endothelial lineage tracing system, based on tdTomato expression driven by EC-specific Cdh5 promoter, in which ECs are fluorescently labeled independent of EC-specific surface marker expression that may be altered by endothelial plasticity in cancer." (PMID 38416830, 2024). "These included, but were not limited to: PECAM1 and CDH5 (EC markers), PDGFRA (fibroblast marker), PDGFRB (pericyte marker), and EPCAM and KRT18 (cancer cell markers)." (PMID 38183074, 2024). "Upon examination of VE-cadherin, ephrin A2, VEGFR2, laminin 5γ2, MMP1, MMP2, MMP9 and MMP14 by the human cancer cells, we made the surprise finding that of the genes investigated, VE-cadherin (CDH5) was the most highly expressed." (PMID 32246008, 2020). "In this review, we will discuss the structural and functional properties of cadherin 5 (CDH5), cadherin 6 (CDH6) and cadherin 17 (CDH17), as well as their pathological implications in cancer progression and metastasis." (PMID 31324051, 2019). "The abundance of genes related to vascular stability (CDH5, CLDN5, TIE1, JAM2, TEK) indicated that the group with a lower cholesterol score had higher vascular stability, while low vascular stability often promotes cancer growth." (PMID 38023262, 2023).
cancer (continued). "CDH5, also known as vascular endothelial CDH, is a member of the transmembrane cadherin superfamily, generally considered to play key roles in the progression of various malignant tumors." (PMID 34917508, 2021). "Also in this case three genes (CDH5, CXorf36, and TIE1) were present in the final cluster in all six cancer sets." (PMID 27809802, 2016). "We also observed the same trend for the mRNA of the mesenchymal marker hFN1, suggesting an increased aggressiveness of cells accompanied by an increase in MMP2 but not MMP9 mRNAs and of the CDH5 gene, fundamental to sustain cancer cell proliferation through vasculogenic mimicry." (PMID 40332096, 2025). "On the contrary, MMP9 seemed completely nonspecific and not correlated to an increase in cancer cell aggressiveness, while other genes such as VIM, CDH5, and MCAM showed a trend toward an increased expression in the metastatic counterpart, albeit not statistically significant." (PMID 40332096, 2025).